MIXL1 (Mix paired-like homeobox)
Description:
Transcription factor that play a central role in proper axial mesendoderm morphogenesis and endoderm formation. Required for efficient differentiation of cells from the primitive streak stage to blood, by acting early in the recruitment and/or expansion of mesodermal progenitors to the hemangioblastic and hematopoietic lineages. Also involved in the morphogenesis of the heart and the gut during embryogenesis. Acts as a negative regulator of brachyury expression (By similarity).
Synonyms: MIXL; MILD1; MIX
Tractability: No criterion of Open Targets' tractability assessment is met for any kind of drug.
Gene: Protein-coding gene on chromosome 1 (226,223,618 to 226,227,060, forward strand). Ensembl gene ENSG00000185155.
Subcellular location: Nucleus
Subcellular location (Human Protein Atlas): Nucleoplasm
Pathways (Reactome):
Developmental Biology: Formation of definitive endoderm; Germ layer formation at gastrulation
Gene Ontology:
Molecular function: RNA polymerase II-specific DNA-binding transcription factor binding; sequence-specific double-stranded DNA binding; cis-regulatory region sequence-specific DNA binding; DNA-binding transcription activator activity, RNA polymerase II-specific; DNA-binding transcription factor activity, RNA polymerase II-specific; RNA polymerase II cis-regulatory region sequence-specific DNA binding; DNA binding; identical protein binding; protein homodimerization activity
Biological process: digestive tract development; endoderm development; endodermal cell differentiation; gastrulation; heart development; hematopoietic progenitor cell differentiation; negative regulation of hematopoietic progenitor cell differentiation; positive regulation of mesoderm development; positive regulation of transcription by RNA polymerase II; regulation of transcription by RNA polymerase II; regulation of DNA-templated transcription
Cellular component: chromatin; nucleus
Genetic constraint (gnomAD): Loss-of-function variants: 9 observed, 6.19 expected, observed/expected ratio (o/e) 1.45, 90% interval 0.84 to 1.92. That is too few expected variants to judge how well the gene tolerates losing a copy. Missense variants: 330 observed, 242.54 expected, observed/expected ratio (o/e) 1.36, 90% interval 1.24 to 1.49. Synonymous variants: 164 observed, 111.4 expected, observed/expected ratio (o/e) 1.47, 90% interval 1.3 to 1.68.
Homologues: Orthologues: chimpanzee MIXL1 (99% identical), macaque MIXL1 (96% identical), pig MIXL1 (81% identical), rabbit MIXL1 (77% identical), mouse Mixl1 (69% identical), rat Mixl1 (68% identical), dog MIXL1 (60% identical), zebrafish mixl1 (30% identical). Paralogues in human: PROP1 (27% identical), ESX1 (26% identical), ALX3 (25% identical), PAX7 (25% identical), PAX6 (24% identical), ARX (24% identical), OTX2 (23% identical), RAX (23% identical), UNCX (23% identical), PAX3 (22% identical), ALX4 (22% identical), OTP (22% identical), and 38 more.
Diseases named in the same sentence as MIXL1 in open-access papers:
MIXL1 is named in the same sentence as 10 diseases in open-access papers, as found by Europe PMC text mining. Sharing a sentence is not in itself a finding about the gene and the disease. The quoted sentences say what the papers report.
acute myelogenous leukemia (1 paper, 2014). "Retrovirally transduced Mixl1 is reported to induce acute myelogenous leukemia (AML) with a high penetrance." (PMID 25544748, 2014).
acute promyelocytic leukemia (1 paper, 2014). An aggressive form of acute myeloid leukemia (AML), characterized by arrest of leukocyte differentiation at the promyelocyte stage, due to a specific chromosomal translocation t(15;17) in myeloid cells. "Lack of MIXL1 expression in AML M3 acute promyelocytic leukemia, frequently associated with the PML-RARA translocation arising in the context of myeloid restricted gene expression program is also consistent with such a model." (PMID 25544748, 2014).
hepatocellular carcinoma (1 paper, 2014). A malignant tumor that arises from hepatocytes. "Mix.1 is induced in Xenopus embryos by BMP4 or activin A in a SMAD5-dependent manner, and MIXL1 can be induced by TGF-β in human hepatocellular carcinoma and in mouse embryonic stem cells." (PMID 25544748, 2014).
lung adenocarcinoma (1 paper, 2021). A carcinoma that arises from the lung and is characterized by the presence of malignant glandular epithelial cells. "Cao and colleagues found that UPF1 may inhibit TGF-β signaling by decreased expression of Smad2/3, MIXL1 and SOX17 in lung adenocarcinoma." (PMID 34922601, 2021).
lung carcinoma (1 paper, 2022). "For the next gene involving two omics levels, MIXL1 (ENSP00000355775), an epigenome analyses in 2019 on circulating tumor cells associated with metastasis revealed that circulating tumor cells in lung cancer has typical epigenomic alterations in MIXL1." (PMID 35155435, 2022). "The gene MIXL1 is regulated by microRNAs from let-7 family during the initiation and proliferation of lung cancer stem cells." (PMID 35155435, 2022).
teratoma (1 paper, 2019). A non-seminomatous germ cell tumor characterized by the presence of various tissues which correspond to the different germinal layers (endoderm, mesoderm, and ectoderm). "The transcriptional analysis of teratoma tissues also showed the expression of genes of all three germ layers: the endoderm (SOX7, and SOX17), mesoderm (BRACHYURY, and MIXL1), and ectoderm (PAX6, and TUJ1)." (PMID 31888235, 2019).
cancer (3 papers, 2012 to 2015). A tumor composed of atypical neoplastic, often pleomorphic cells that invade other tissues. "Furthermore, MIXL1 expression is detected in the cancer genome atlas (TCGA) AML samples in a pattern mutually exclusive from that of HOXA9, CDX2 and HLX suggesting the existence of a core, yet distinct HOX transcriptional program." (PMID 25544748, 2014).
infection (1 paper, 2025). The state of being infected such as from the introduction of a foreign agent such as serum, vaccine, antigenic substance or organism. "Conversely, expression levels of ectodermal (Pax6, Gfap, Neurod1, and Olig1) or mesendoderm (Flk1, Eomes, Hnf1b, and Mixl1) markers either not enhanced or only weakly increased after Cre infection." (PMID 40216251, 2025).
MIXL1 also shares sentences with these, for which no sentence is quoted: tumor (2 papers); COVID-19 (1).